DPP4 (dipeptidyl peptidase 4)
Diseases named in the same sentence as DPP4 in open-access papers (continued):
Sharing a sentence is not in itself a finding about the gene and the disease.
COVID-19 (continued). "Then, we provide the rationale for investigation of vitamin D and DPP-4 inhibitor combination therapy (VIDPP-4i) as an immunomodulation strategy to ratchet down the virulence of SARS-CoV-2, prevent disease progression and modulate the cytokine storm in COVID-19." (PMID 33906375, 2021). "Thus, DPP-4 inhibition may have the potential to counteract the DPP-4-mediated SARS-CoV-2 hijacking and virulence and to improve clinical outcomes of COVID-19 by interfering with the interaction between SARS-CoV-2 and target host cells." (PMID 33906375, 2021). "The clinical course of COVID-19 may also be modulated by the type of antidiabetic drug the patient is receiving, as SGLT2 inhibitors and GLP1R agonists could exacerbate the infection while DPP4 inhibitors may act as mitigators." (PMID 35126141, 2021). "In addition, both DPP-4 and ACE2 are dysregulated proteins in diabetes, so it may be possible for diabetic patients to present more severe cases of COVID-19 due to the increased levels of these proteases." (PMID 33791232, 2021). "In this review focused on biguanides, thiazolidinediones, sulfonylureas, dipeptidyl peptidase-4 (DPP4) inhibitors, glucagon-like peptide-1 receptor (GLP-1R) agonists, sodium-glucose cotransporter-2 (SGLT2) inhibitors and insulin, their profiles will be discussed in relation to COVID-19." (PMID 33195481, 2020). "DPP-4/CD26 receptor expression can be reduced in vivo by correction of hypovitaminosis D, further suggesting that optimization of vitamin D status could improve the outcome COVID-19 patients." (PMID 32904892, 2020). "Furthermore, due to their vascular effects, both DPP4 and ACE2/Ang II axis arise as potential therapeutic targets to ARDS and CV complications in COVID-19 that might be pharmacologically scoped, as it will be detailed below." (PMID 32848769, 2020). "When considering variables prior to admission, our results support no independent association between a severe course of COVID-19 and age, sex, long-term glucose control, chronic complications, hypertension or usual medications, including RAAS blockers and DPP-4 inhibitors." (PMID 32472191, 2020). "Conversely, although not univocal, some evidence suggests that DPP4 inhibitors may retain the potential for preventing and/or mitigating the clinical course of COVID-19." (PMID 32456064, 2020). "These pleiotropic anti-i nflammatory and anti-fibrotic actions of DPP-4 inhibitors are not analogous to those of the standard anti-i nflammatory agents (such as corticosteroids) and may provide a helpful tool in COVID-19 therapy owing to their other positive actions." (PMID 39526061, 2024). "Furthermore, the authors reveal prior significant, unreported correlations between circulating DPP4 activity and CRP, D-dimer, IL-6 and peripheral blood lymphocyte count, which are all essential parameters currently used in the everyday clinical care of COVID-19 patients." (PMID 35195023, 2022). "Considering all this together, there is a scientific questions about the beneficial effect that the use of DPP-4 inhibitors could have in patients with COVID-19, however, no prospective and comparative studies have been performed to more clearly dilucidated this scientific concern." (PMID 35017617, 2022). "Moreover, a prospective study with 89 COVID-19 but non-diabetic patients demonstrated that sitagliptin improved clinical outcomes, radiological scores, and inflammatory biomarkers, pointing to a potential usefulness of DPP4 inhibitors in managing non-diabetic COVID-19 patients." (PMID 36009573, 2022). "Likewise, the anti-inflammatory/immunomodulatory effects of (hydroxy)chloroquine, statins, DPP-4 inhibitors, macrolides, nafamostat, clindamycin, doxycycline, JAK inhibitors, rhACE2, and heparins are of enormous significance given the reported excessive inflammation in the severe cases of COVID-19." (PMID 32718020, 2020).
COVID-19 (continued). "However, it does not exclude the possibility that DPP4 inhibition may indirectly attenuate the severity of COVID-19, due to the role that DPP4 plays in the pathophysiology of common comorbidities in patients with COVID-19, including hypertension." (PMID 33329052, 2020). "At least one study, however, has shown that patients taking DPP-4 inhibitors required less intubation (43%) than non-users (81%), suggesting a beneficial role of DPP-4 inhibitors in COVID-19." (PMID 37064327, 2023). "In spite of this, the clinical outcomes of COVID-19 patients using DPP4 inhibitors only was not significantly different from that using both DPP4 inhibitors and RAS inhibitors and was notably improved from COVID-19 T2DM patients without medication." (PMID 36009573, 2022). "In that study, the COVID-19-related mortality in T2DM was significantly lower in patients prescribed metformin, SGLT2 inhibitors, and SU and higher in patients prescribed DPP-4 inhibitors and insulin vs. those not prescribed these medications." (PMID 36017317, 2022). "Hariyanto performed a meta-analysis on the application of DPP4 inhibitors in COVID-19 patients with T2DM, and the results showed that there was no beneficial outcome compared to patients without DPP4 inhibitor treatment." (PMID 34955820, 2021). "With that in mind, we would like to voice our concerns over chronic implications following recovery from COVID-19, especially not only in diabetic but also in non-diabetic patients, and to indicate that some preventive measures could be undertaken by application of DPP-4 inhibitors." (PMID 32848788, 2020). "Thus, AT from obese patients highly expresses DPP4 and possibly is its major circulating source, which may facilitate the entry of SARS-CoV-2 into cells and also strong inflammation and violent immune response, important steps leading to the cytokine storm of COVID-19." (PMID 32806722, 2020). "While in vitro/in vivo evidence of utilization of DPP4 by SARS-CoV-2 remains lacking, clinical studies using DPP4 inhibitors have shown a reduction in respiratory complications, a decrease in mortality, and complications in COVID-19 patients." (PMID 40431702, 2025). "Independent of the potential role of DPP4 as SARS-CoV-2 receptor, DPP4 might have a role in COVID-19 incidence and physiopathology by regulating glucose homeostasis." (PMID 36009573, 2022). "The lack of positive effects on mortality due to COVID-19 and severe disease related to COVID-19 may be due to the ineffectiveness of DPP-4i on the soluble form of DPP-4." (PMID 36199855, 2022). "Although in silico experiments that predict the compatible binding between DPP4 and S glycoprotein of SARS-CoV-2 have not been demonstrated to date in vitro or in vivo, the impact of DPP4 on the COVID-19 physiopathology goes further, due to the multiple functions developed by the protease." (PMID 36009573, 2022). "While the DPP-4/CD26 receptor has not been confirmed as a target for COVID-19, the genetic similarity of MERS 2 and COVID-19, justifies considering this receptor a putative secondary adhesion molecule for COVID-19 host cell invasion." (PMID 32912355, 2021). "Thus, testosterone may increase COVID-19 severity through the DPP4/CD26 pathway; however, there is no study related to DPP4/CD26 and testosterone in SARS-CoV-2 infection." (PMID 34568081, 2021). "Furthermore, targeting TLRs, CLRs, and other receptors (Ezrin and dipeptidyl peptidase-4) that do not directly engage SARS-CoV-2 S protein, but may contribute to augmented anti-viral immunity and viral clearance, may represent therapeutic targets against COVID-19." (PMID 33498183, 2021).
Insulin resistance (194 papers, 2010 to 2025). Increased resistance towards insulin, that is, diminished effectiveness of insulin in reducing blood glucose levels. "It has been found that upregulation of hepatic DPP-4 ex-pression is likely the cause of glucose intolerance or insulin resistance." (PMID 41155701, 2025). "This dysregulation led to a reduction in insulin sensitivity, as evidenced by a significant increase in the activity of key enzymes associated with insulin resistance, such as DPP-4 and PTP1B." (PMID 40376699, 2025). "Insulin resistance, FL, elevated blood pressure, and oxidative stress have all been linked to DPP4, an enzyme with diverse physiological functions." (PMID 40249657, 2025). "Circulating DPP4/CD26 has been proposed as a novel adipokine and a marker of visceral obesity and insulin resistance, revealing a strong association with pre-diabetic disorders." (PMID 39273582, 2024). "Given the close relationship between circulating DPP-4 and insulin resistance, it is strongly associated with the onset and development of T2D, as confirmed in cohort studies." (PMID 38476668, 2024). "Rats with DPP-4 deficiency display enhanced adiponectin levels along with attenuated adipose tissue inflammation and insulin resistance." (PMID 39054499, 2024). "Apart from its capability to degrade incretins, circulating DPP-4 is also recognized as an adipokine associated with insulin resistance and T2D pathogenesis." (PMID 38476668, 2024). "Several studies show that sDPP4 levels are associated with the presence of insulin resistance in both animal models and humans, and experimental data point towards a role of DPP4 as a proper mediator, and not only a biomarker, of impaired insulin sensitivity." (PMID 36140405, 2022). "As a result, DPP4 deficiency in mice manifests in improved glucose tolerance and decreased obesity and insulin resistance." (PMID 35821802, 2022). "DPP4 expression is directly associated with insulin resistance (IR), especially in visceral adipose tissue, in lean and obese individuals." (PMID 35885620, 2022). "As we know, this is the first time AE was reported useful to improve the fatty liver associated with insulin resistance, via regulating DPP-4." (PMID 35290413, 2022). "In HFD/streptozotocin-induced diabetic rat, lower serum DPP-4 levels were associated with improved insulin resistance and improved beta cell function." (PMID 34203048, 2021). "Knocking down the expression of DPP4 in hepatocytes through AAV-encoded short hairpin RNA against DPP4 suppresses inflammation of visceral adipose tissue and insulin resistance in obese mice." (PMID 34385484, 2021). "Hepatocyte-specific overexpression of DPP4 is associated with hepatic insulin resistance and liver steatosis." (PMID 33691757, 2021). "Obesity was said to be associated with insulin resistance, and one of the factors that influence the insulin secretion is the blood glucose level and the expression of dipeptidyl-peptidase 4 (DPPIV) protein, which involves in the glucose metabolism." (PMID 33029159, 2020). "A recent study found that markers of higher insulin resistance, including triglyceride, are consistently associated with reduced glycemic response to DPP-4 inhibitors in T2DM patients with DPP-4 inhibitor monotherapy." (PMID 31485457, 2019). "We also examined the effects of DPP-4 inhibition in IRS-1-deficient mice fed an SL or SO diet as a model of insulin resistance." (PMID 26937254, 2016). "Recent data suggest that the protein level of DPP4 is significantly associated with insulin resistance factors and components of metabolic syndrome." (PMID 24647445, 2014). "For instance, a high-fat diet leads to insulin resistance causing the reduced level of serine exopeptidase (Dpp4, Dipeptidyl-peptidase 4), which is known to leaven neuronal insulin receptor function, brain mitochondrial function and cognitive function in rats." (PMID 25423262, 2014).
Insulin resistance (continued). "Additionally, this allele has been associated with a reduced risk of hypoalphalipoproteinemia, insulin resistance, and hyperinsulinemia, along with decreased serum DPP4 levels." (PMID 40249657, 2025). "Clinical trials studying the effect of DPP-4 inhibitors on GDM have demonstrated a reduction in insulin resistance, alleviation of the symptoms associated with hyperglycemia, reduction in fasting plasma glucose and serum insulin, and downregulation of a biomarker indicative of glucose intolerance." (PMID 38339106, 2024). "Thus, in mice, hepatocyte-specific overexpression of DPP4 is associated with hepatic insulin resistance and liver steatosis, whereas knockdown of DPP4 improves insulin sensitivity and reduces lipid accumulation in cultured hepatocytes." (PMID 33691757, 2021). "A direct association exists between DPP4 activity and insulin resistance in humans." (PMID 33691757, 2021). "Weekly administration of the DPP4 inhibitor OMG in ameliorating hepatic insulin resistance may cause beneficial effects in liver with NAFLD/NASH." (PMID 33691757, 2021). "Additionally, both DPP4 minor alleles were associated with protection for the presence of insulin resistance (IR) (OR = 0.17, Pheterozygote = 0.019 for rs12617336 and OR = 0.75, Padditive = 0.049 for rs17574)." (PMID 34178021, 2021). "Thus, in mice, hepatocyte-specific overexpression of Dpp4 is associated with hepatic insulin resistance and liver steatosis, whereas knockdown of Dpp4 results in improved insulin sensitivity and reduced lipid accumulation in cultured hepatocytes." (PMID 30828317, 2019). "Furthermore, DPP4 activity was associated with all insulin resistance markers herein tested (i.e., we found direct associations with fasting insulin and HOMA-IR and inverse associations with SHBG and QUICKI)." (PMID 30886868, 2019). "We suppose that constitutive DPP4 activity might be directly associated not only with fat mass and markers of insulin resistance but also with lean mass." (PMID 30886868, 2019). "Since lean mass is inversely related to insulin resistance, our findings that DPP4 activity is positively associated with lean mass and also with measures of central obesity and insulin resistance might seem paradoxical." (PMID 30886868, 2019). "silenced hepatocyte Dpp4 and demonstrated reduced adipose tissue inflammation and insulin resistance in obese mice." (PMID 40771104, 2025). "The insulin resistance-attenuating effect of LASSBio-2129 can be generated through daily glycemic control by inhibiting the DPP-4 enzyme, which is known to prolong the half-life of GLP-1 and GIP, thereby corroborating the effect observed in this study." (PMID 41155701, 2025). "The expression of DPP4, annotated by cg09601770 in the first exon region, is influenced by methylation and has been shown to increase in obese individuals, contributing to insulin resistance." (PMID 40702573, 2025). "There is evidence that hepatic DPP-4 activity/expression is increased in conditions of glucocorticoid-induced insulin resistance." (PMID 41155701, 2025). "The experimental data suggest that DPP-4 is modulated in a tissue-specific manner and depends on hyperglycemia and insulin resistance." (PMID 40142315, 2025). "Metformin is known to attenuate insulin resistance, while DPP-4 inhibitors improve islet dysfunction by preserving the biological activity of endogenous GLP-1." (PMID 40390755, 2025). "In a cohort study, increased circulating DPP-4 activity predicted the development of insulin resistance and the incidence of T2D in Chinese adults over 4 years." (PMID 38476668, 2024). "Here, we further demonstrated that the injection of IL-10-treated SVFs into the adipose tissue of Leprdb/db mice decreased proinflammatory cytokine expression, suppressed plasma DPP4 activity, and ameliorated insulin resistance." (PMID 39125659, 2024).
Insulin resistance (continued). "A study revealed that pioglitazone was significantly better at alleviating insulin resistance and inferior at improving β-cell function compared with DPP-4 inhibitors in patients with T2DM under similar glycemic control." (PMID 38336931, 2024). "In T2DM, heightened DPP-4 promotes insulin resistance and hyperglycemia by degrading GLP-1, potentially impairing cognitive function and elevating AD risk." (PMID 39766390, 2024). "Gemigliptin, a dipeptidyl peptidase‐4 (DPP‐4) inhibitor, was able to relieve hepatic steatosis and insulin resistance by suppressing LECT2 expressions involved in increased AMPK phosphorylations in HFD‐fed mice." (PMID 35656863, 2022). "Elevated DPP4 activity is a risk factor for developing metabolic syndrome and T2DM and is associated with insulin resistance." (PMID 35821802, 2022). "CD26/DPP4 has been reported to attenuate anticancer immunity via chemokine cleavage and to promote insulin resistance and inflammation in the liver and/or adipose tissue via dysregulation of macrophage M1/M2 polarization." (PMID 35053615, 2022). "In adipocytes, treatment with DDP4 induced dose-dependent decrease of insulin-stimulated Akt phosphorylation, and consequent insulin resistance, demonstrating an autocrine effect of DPP4 in these cells." (PMID 36140405, 2022). "As an ultimate result, DPP4-dysregulated activity induces insulin resistance and chronic low-grade inflammation, particularly within the adipose tissue." (PMID 36140405, 2022). "The AE subfractions F1 and F2 effectively attenuated DPP4 activation and the cascades of insulin resistance in liver cells." (PMID 35290413, 2022). "Recently, CD26/DPP4 has been reported to attenuate anticancer immunity via chemokine cleavage and to promote insulin resistance and inflammation in the liver and/or adipose tissue via dysregulation of macrophage M1/M2 polarization." (PMID 35053615, 2022). "In the same study, circulating DPP-4 concentration in insulin-sensitive obese patients was significantly lower than in those with insulin resistance." (PMID 35205155, 2022). "Hepatic DPP4 is important in insulin resistance and the anti-diabetic effect of DPP4 inhibitors is mediated by upregulation of intact GLP-1." (PMID 35655996, 2022). "Due to its broad enzymatic activity, DPP4 is not only involved in the pathogenesis of T2DM but also participates in insulin resistance, fatty liver, hypertension, and oxidative stress." (PMID 35885620, 2022). "The incretin-degrading activity of DPP4 represents a potential link between dysmetabolism and insulin resistance." (PMID 35190847, 2022). "DPP4 induces insulin resistance independently of its effect on glucagon-like peptide 1, thus it is conceivable that DPP4 directly contributes to metabolic dysfunction in patients with morbid obesity." (PMID 33538983, 2021). "We found that change from daily DPP4 inhibitors to OMG appears to offer benefits for NAFLD patients along with decreased insulin resistance and inflammation." (PMID 33691757, 2021). "Other studies have pointed toward DPP4 acting as a hepatokine, linking the liver and adipose tissue with the development of insulin resistance, and glucose intolerance." (PMID 33691757, 2021). "In this study, we examined the involvement of adipose tissue M1/M2 cytokine expression in plasma DPP4 activity, systemic inflammation, and insulin resistance in a diabetic mouse model." (PMID 34043673, 2021). "Dpp4 inhibitors increase the biological activity of incretin hormones, thereby increasing the half-life of insulin and improving insulin resistance." (PMID 34094026, 2021). "Hepatic overexpression of DPP4 in mice on a high-fat diet led to hepatic insulin resistance accompanied by hepatic steatosis and liver damage as well as increased body weight, fat mass, adipose tissue inflammation, and hypercholesterolemia." (PMID 33538983, 2021).